DMAC2L (distal membrane arm assembly component 2 like)
Description:
Involved in regulation of mitochondrial membrane ATP synthase. Necessary for H(+) conduction of ATP synthase. Facilitates energy-driven catalysis of ATP synthesis by blocking a proton leak through an alternative proton exit pathway.
Synonyms: FB; ATP5S; ATPW; HSU79253
Tractability: No criterion of Open Targets' tractability assessment is met for any kind of drug.
Gene: Protein-coding gene on chromosome 14 (50,312,301 to 50,335,558, forward strand). Ensembl gene ENSG00000125375.
Subcellular location: Mitochondrion; Mitochondrion inner membrane
Subcellular location (Human Protein Atlas): Mitochondria; Nucleoplasm
Pathways (Reactome):
Metabolism: Formation of ATP by chemiosmotic coupling
Organelle biogenesis and maintenance: Cristae formation
Gene Ontology:
Molecular function: proton transmembrane transporter activity
Biological process: proton transmembrane transport
Cellular component: mitochondrion; mitochondrial inner membrane
Genetic constraint (gnomAD): Loss-of-function variants: 20 observed, 22.1 expected, observed/expected ratio (o/e) 0.9, 90% interval 0.64 to 1.32. The upper end of that interval is the gene's LOEUF score, 1.32, which puts it in group 5 of 6, group 1 being the genes least tolerant of losing a copy. Missense variants: 231 observed, 253.44 expected, observed/expected ratio (o/e) 0.91, 90% interval 0.82 to 1.02. Synonymous variants: 85 observed, 93.74 expected, observed/expected ratio (o/e) 0.91, 90% interval 0.76 to 1.09.
Homologues: Orthologues: macaque DMAC2L (94% identical), dog DMAC2L (90% identical), guinea pig DMAC2L (90% identical), rabbit DMAC2L (88% identical), pig DMAC2L (88% identical), mouse Dmac2l (78% identical), chimpanzee DMAC2L (74% identical), rat Dmac2l (74% identical), tropical clawed frog dmac2l (65% identical), zebrafish dmac2l (60% identical), Drosophila melanogaster CG10731 (32% identical), Caenorhabditis elegans R02D5.8 (30% identical), and 1 more.
Diseases named in the same sentence as DMAC2L in open-access papers:
DMAC2L is named in the same sentence as 4 diseases in open-access papers, as found by Europe PMC text mining. Sharing a sentence is not in itself a finding about the gene and the disease. The quoted sentences say what the papers report.
bipolar disorder (1 paper, 2023). A disorder of the brain that causes unusual shifts in mood, energy, activity levels and the ability to carry out day-to-day tasks. "Potential candidate genes for bipolar disorder with metabolic syndrome were found in 5 candidate genes (AP1G2, C1orf54, DMAC2L, RABEPK and ZFAND5), all of which have diagnostic significance." (PMID 37860165, 2023).
DMAC2L also shares sentences with these, for which no sentence is quoted: breast carcinoma (1 paper); metabolic syndrome (1); periodontitis (1).